ENAH (ENAH actin regulator)
Diseases named in the same sentence as ENAH in open-access papers (continued):
Sharing a sentence is not in itself a finding about the gene and the disease.
cancer (23 papers, 2013 to 2024). A tumor composed of atypical neoplastic, often pleomorphic cells that invade other tissues. "To disseminate, cancer cells must express MenaINV, an isoform of the actin regulatory protein Mena, encoded by the ENAH gene, that endows tumor cells with transendothelial migration activity, allowing them to enter and exit the blood circulation." (PMID 37024946, 2023). "Multiple splice variants of ENAH gene have been identified and are involved in several mechanisms critical for cancer progression." (PMID 34571790, 2021). "ENAH deficiency in mouse models of cancer has been shown to decrease metastasis by reducing tumor cell invasion and intravasation." (PMID 34854809, 2021). "Enabled homolog (ENAH) is an actin-binding protein that implicated in multiple malignant tumors." (PMID 35030977, 2022). "As a protein associated with OSCC progression, ENAH is significantly increased in OSCC tissues and correlates with worse survival outcomes for cancer patients." (PMID 39511483, 2024). "ENAH splice variants containing alternative exons ++ and +++ (Mena INV), linked to cancer cell invasiveness, have also been described." (PMID 33672325, 2021). "Differently from all other members of Ena/VASP, there are multiple splice variants of the MENA gene, enabled homolog (ENAH), which are involved in several mechanisms critical for cancer progression." (PMID 33672325, 2021). "A wealth of studies has attributed EMT to alternative splicing (AS) of a plethora of cancer-associated genes, including CD44, FGFR2, hMENA (also known as ENAH) and p120 catenin." (PMID 33089214, 2020). "Recent studies show overexpression of protein enabled homolog (ENAH) in several cancer types, and it has been shown to correlates with tumor invasiveness." (PMID 31945087, 2020). "Recent studies show overexpressed ENAH in several cancer types, and ENAH correlates with tumor invasiveness." (PMID 29069803, 2017). "Combining EGFR inhibition with targeting ENAH signaling could potentially improve the response rates to cancer treatments." (PMID 39511483, 2024). "This suggests that the failure of EGFR-based cancer treatment may be partly attributed to ENAH-mediated AKT activation." (PMID 39511483, 2024). "Among the dysregulated proteins in cancer tissues, protein-enabled homolog (ENAH) was selected for further investigation due to its elevated levels in primary cancer tissues compared to adjacent noncancerous tissues and its persistent overexpression in PDX tumor tissues." (PMID 39511483, 2024). "Focusing on the EVH1 domain of human ENAH, an actin regulator that is highly expressed in invasive cancers, we screened 36-residue proteome-derived peptides and discovered new interaction partners of ENAH and diverse mechanisms by which context influences binding." (PMID 35076015, 2022). "There are some examples highlighting the important role of ENAH in cancers." (PMID 35030977, 2022). "ENAH and CD44 are amongst the most studied splicing events impacting cancer and are well-known biomarkers of poor prognosis." (PMID 33845831, 2021). "Specific isoforms of CD44, ENAH actin regulator (ENAH), Kruppel-like factor 6 (KLF6), recepteur d’Origine nantais (RON) tyrosine kinase, and Rac family small GTPase 1 (RAC1) can promote cancer cell invasion and migration." (PMID 34771719, 2021). "Five of these 25 alternatively spliced genes are well-known to play a role in cancer (ARHGEF11, CD44, CTNND1, ENAH, MBNL1)." (PMID 33845831, 2021). "In EMT, ESRP1 was thought to directly regulate these subtypes such as FGFR2, ENAH, CD44 and CTNND, thereby losing cell-to-cell adhesion and polarity, increasing cancer cell invasion and migration." (PMID 32467669, 2020). "Thus, QKI may play a dual role in cancer progression, limiting the initial formation of tumours but increasing their subsequent invasiveness through regulating the splicing of different target genes, such as through promotion of mesenchymal ENAH splicing." (PMID 29871889, 2018).
cancer (continued). "Many of these isoforms (including CD44, ENAH, p120-Catenin, EPB41L5) show direct correlation with both MET-EMT and metastasis, in multiple cancer types." (PMID 24124593, 2013). "There are many AS events involves in EMT during cancer progression, such as splicing of FGFR2, CD44, CTNND1, and ENAH and they may become therapeutic points- it is therefore timely to ask ourselves: Can these AS events in EMT be targets of cancer therapy?" (PMID 38002944, 2023). "Therefore, results of the current study add to the evidence that ENAH is involved in the proliferation, migration, and invasion of ESCC in addition to other types of cancers." (PMID 32698859, 2020). "ENAH was identified as a candidate associated with OSCC progression based on integrated analyses, which showed increased ENAH levels in primary OSCC tissues compared with adjacent noncancerous counterparts, and sustained overexpression in the cancer tissues of PDX models." (PMID 39511483, 2024).
tumor (23 papers, 2007 to 2026). "ENAH expression markedly associated with tumor size (P < 0.001), T stage (P < 0.001), N stage (P = 0.001), TNM stage (P < 0.001) and prognosis (P < 0.001)." (PMID 29069803, 2017). "Overexpression of ENAH has been associated with tumor progression and poor survival in OSCC." (PMID 39511483, 2024). "In this study, bioinformatics analysis showed that in the four datasets (GSE3524, GSE74530, GSE138206, and 399 TCGA in OSCC patients), the expression of ENAH (the gene encoding MENA protein) in tumor tissues was significantly higher than that in normal tissues." (PMID 36620546, 2022). "Furthermore, immunohistochemical analyses of clinical GC paraffin specimens showed that ENAH expression was significantly associated with tumor infiltration and local lymph node metastasis." (PMID 29069803, 2017). "We demonstrated with the studied patient cohort and the conditional cell model that expression of ESRP1 in CRC tumor cells is associated with a shift in EMT splicing patterns of ENAH and CTNND1 (p120-catenin), thus confirming a key role of ESRPs in CRC progression." (PMID 27650542, 2016). "By Student's t-test analysis, ENAH was discovered to be distinctly up-regulated in HCC tumor tissues in comparison with normal tissues." (PMID 35030977, 2022). "ENAH’s inhibition decreases metastasis by slowing down tumour progression and reducing cell invasion and intravasation." (PMID 33845831, 2021). "Hsa_circ_0030018, as the sponge for miR-599, promotes the high expression of enabled homolog (ENAH) in EC cells and promotes tumor progression." (PMID 33627631, 2021). "Relative to normal saline treatment, exo-miR-375 agomir or exo-NC-agomir administration elevated E-cadherin expression, and decreased the expression of ENAH, Ki-67 and Bcl-2 in the tumor tissues, of which exo-miR-375 agomir led to more pronounced alterations." (PMID 32698859, 2020). "In the current study, we found mRNA and protein expression of ENAH were significantly higher in primary GC tissues compared with adjacent non-tumor tissues." (PMID 29069803, 2017). "The ENAH mRNA expression level was significantly higher in 22 (61.1%) GC tissues compared with the adjacent non-tumor tissues (P = 0.0283)." (PMID 29069803, 2017). "Herein, in a large GC population (238 cases), we found that the expression of ENAH was significantly correlated with tumor size (P < 0.001), tumor infiltration (P < 0.001), local lymph node metastasis (P = 0.001), and TNM stage (P < 0.001)." (PMID 29069803, 2017). "ENAH expression was significantly correlated with depth of tumor infiltration (T stage, P = 0.023) and age (P = 0.003)." (PMID 29069803, 2017). "TCGA data analyses also showed that ENAH expression was significantly correlated with the depth of tumor infiltration (P = 0.023), further supporting our proposal that ENAH plays important roles in the progression and dedifferentiation of GC." (PMID 29069803, 2017). "In this study, an increased SRGAP2C: SRGAP2 transcript ratio or decreased expression of ENAH was found in all juvenile metastatic lesions (n = 7) compared to osteoblasts and primary tumor samples (n = 5)." (PMID 27966608, 2016). "Reduction of ESRP1 in tumor cells was evaluated by immunohistochemistry, associated with microsatellite stability and switch to mesenchymal splice signatures of FGFRs, CD44, ENAH and CTNND1(p120-catenin)." (PMID 27650542, 2016). "ENAH expression correlates with tumor grade and vascular invasion in salivary tumor." (PMID 29069803, 2017). "Chi-square analyses revealed that ENAH expression was significantly correlated with tumor size (P < 0.001), depth of tumor infiltration (T stage, P < 0.001), local lymph node metastasis (N stage, P = 0.001), and TNM stage (P < 0.001), but not with age, gender, and distant metastasis (M stage)." (PMID 29069803, 2017). "Similar to LASP-1, there is a significant correlation of ENAH-expression and tumor size (p < 0.05)." (PMID 17956604, 2007).
tumor (continued). "However, in this case–control study, the ENAH level in OSCC tissues was not statistically associated with tumor size, lymphatic metastasis, overall stage, perineural invasion, cell differentiation, or lymphovascular invasion." (PMID 39511483, 2024). "Notably, the expression of ENAH is correlated with vascular invasion, tumor grade, and unfavorable prognosis, which suggests that ENAH might participate in carcinogenesis and tumor progression." (PMID 35012558, 2022). "Collectively, these results establish the 3‐gene (ENAH, AXL and GAS6) expression signature as a prognostic indicator, hallmark of an aggressive disease in PDAC and LUSC patients and strengthen the clinical relevance of the hMENA expression pattern analysis in both tumor cells and CAFs." (PMID 32909687, 2020). "Univariate Cox regression analyses showed that tumor size (P < 0.001), T stage (P < 0.001), N stage (P < 0.001), M stage (P < 0.001), TNM stage (P < 0.001) and ENAH expression (P < 0.001) were significant prognostic factors." (PMID 29069803, 2017). "A multivariate Cox regression analysis confirmed tumor size (P = 0.036), TNM stage (P < 0.001), and ENAH expression (P = 0.019) as independent prognostic predictors for GC patients." (PMID 29069803, 2017). "Overexpression of ENAH in the invasive front of CRC was already identified and suspected to have a role in the initial steps of tumor invasion from primary sites." (PMID 27650542, 2016). "Of note, FLNA and ENAH were both hubs and upregulated in HNSCC, increasing the likelihood that they could play a key role in tumor development." (PMID 37686696, 2023).
infection (1 paper, 2023). The state of being infected such as from the introduction of a foreign agent such as serum, vaccine, antigenic substance or organism. "At 48 h post infection, there was a significant decrease in both ABI1 (p < 0.001) and ENAH (p < 0.01) expression." (PMID 37376546, 2023).
ENAH also shares sentences with these, for which no sentence is quoted: melanoma (2 papers); asthma (1); brain tumor (1); cervical carcinoma (1); Fibroadenoma (1); glioma (1); glomerulopathies (1); human papillomavirus infection (1); lung carcinoma (1); lymph node metastasis (1); metastatic tumor (1); nephrotic syndrome (1); viruses infection (1).